PRICKLE1 (prickle planar cell polarity protein 1)
Description:
Involved in the planar cell polarity pathway that controls convergent extension during gastrulation and neural tube closure. Convergent extension is a complex morphogenetic process during which cells elongate, move mediolaterally, and intercalate between neighboring cells, leading to convergence toward the mediolateral axis and extension along the anteroposterior axis. Necessary for nuclear localization of REST. May serve as nuclear receptor.
Synonyms: RILP; FLJ31937; EPM1B
Tractability: PROTAC: ubiquitination databases record sites on it; its protein half-life has been measured.
Gene: Protein-coding gene on chromosome 12 (42,456,753 to 42,590,355, reverse strand). Ensembl gene ENSG00000139174.
Subcellular location: Nucleus membrane; Cytoplasm, cytosol
Subcellular location (Human Protein Atlas): Nucleoplasm; Basal body; Cytosol
Pathways (Reactome):
Signal Transduction: Asymmetric localization of PCP proteins
Gene Ontology:
Molecular function: protein binding; protein-containing complex binding; zinc ion binding
Biological process: negative regulation of canonical Wnt signaling pathway; negative regulation of cardiac muscle cell myoblast differentiation; negative regulation of DNA-templated transcription; neural tube closure; positive regulation of proteasomal ubiquitin-dependent protein catabolic process; positive regulation of protein ubiquitination; protein import into nucleus; Wnt signaling pathway, planar cell polarity pathway; animal organ morphogenesis; anterior visceral endoderm cell migration; apoptotic process; axis elongation; axonogenesis; basement membrane organization; bone mineralization; cardiac muscle cell development; cell migration; cell-cell adhesion; cilium assembly; cilium organization; cornea development in camera-type eye; cytoskeleton organization; cytoskeleton-dependent intracellular transport; dendrite development; embryonic brain development; and 38 more
Cellular component: cytosol; nuclear membrane; nucleus; cell trailing edge; glutamatergic synapse; membrane; postsynaptic density; proteasome complex
Genetic constraint (gnomAD): Loss-of-function variants: 13 observed, 74.1 expected, observed/expected ratio (o/e) 0.18, 90% interval 0.11 to 0.28. The upper end of that interval is the gene's LOEUF score, 0.28, which puts it in group 1 of 6, group 1 being the genes least tolerant of losing a copy. Missense variants: 808 observed, 1,067.4 expected, observed/expected ratio (o/e) 0.76, 90% interval 0.71 to 0.8. Synonymous variants: 353 observed, 397.22 expected, observed/expected ratio (o/e) 0.89, 90% interval 0.81 to 0.97.
Gene-disease validity (ClinGen):
ClinGen rates the evidence that PRICKLE1 causes each of these diseases.
progressive myoclonus epilepsy (autosomal recessive): Limited. A rare group of disorders characterized by the development of myoclonic and tonic-clonic epileptic seizures associated with progressive degeneration of the nervous system.
epilepsy (autosomal dominant): Disputed. A brain disorder characterized by episodes of abnormally increased neuronal discharge resulting in transient episodes of sensory or motor neurological dysfunction, or psychic dysfunction.
Homologues: Orthologues: chimpanzee PRICKLE1 (99% identical), macaque PRICKLE1 (99% identical), dog PRICKLE1 (97% identical), guinea pig PRICKLE1 (96% identical), pig PRICKLE1 (95% identical), rat Prickle1 (93% identical), mouse Prickle1 (93% identical), tropical clawed frog prickle1 (81% identical), rabbit PRICKLE1 (81% identical), zebrafish prickle1a (67% identical), zebrafish prickle1b (65% identical), Caenorhabditis elegans tes-1 (15% identical), and 2 more. Paralogues in human: TES (16% identical), LMCD1 (12% identical), LIMD2 (3% identical).
Diseases named in the same sentence as PRICKLE1 in open-access papers:
PRICKLE1 is named in the same sentence as 51 diseases in open-access papers, as found by Europe PMC text mining. Sharing a sentence is not in itself a finding about the gene and the disease. The quoted sentences say what the papers report.
breast carcinoma (8 papers, 2016 to 2024). "We have previously shown that PRICKLE1 upregulation is associated with poor MFS in basal breast cancer, a molecular subtype mainly composed of TNBC." (PMID 30971775, 2019). "PRICKLE1 knockdown in basal breast cancer cells led to decreased cell migration and proliferation, the formation of thick actin bundles, and the increased activity of ß1-integrin at the cellular surface." (PMID 39727954, 2024). "Depletion of either PRICKLE1 or MINK1 in breast cancer cells has been demonstrated to reduce cell motility by promoting the formation of dense actin bundles and cellular spreading." (PMID 39123414, 2024). "On the one hand, it has been found that PRICKLE1 is highly expressed in breast cancer and its upregulation correlates with increased phosphorylation of AKT and its downstream components." (PMID 36861110, 2022). "It was also shown that upregulation of PRICKLE1 is associated with AKT signaling and poor prognosis in basal breast cancers." (PMID 29455662, 2018). "Disruption of the PRICKLE1-RICTOR interaction resulted in a strong impairment of breast cancer cell dissemination in xenograft assays." (PMID 29455662, 2018). "PRICKLE1 upregulation was related to poor metastasis-free survival in basal breast cancers." (PMID 39727954, 2024). "Altogether, these data demonstrate the importance of PRICKLE1 and its associated protein complex as poor-prognosis markers in TNBC and provide evidence that PRICKLE1 may be a suitable therapeutic target for treatment of this aggressive subtype of breast cancer." (PMID 30971775, 2019). "It has been shown that the adaptor PRICKLE1 interacts with RICTOR, controls actin cytosqueleton organization and contributes to breast cancer cells dissemination." (PMID 29455662, 2018). "For example, increased expression of PRICKLE1 has been shown to promote cell migration and invasion in breast cancer, gastric cancer, and leukaemia, or PRICKLE4 in the Stem-A molecular subtype of breast cancer, together conferring an unfavourable prognosis." (PMID 37358815, 2024).
hepatocellular carcinoma (6 papers, 2016 to 2024). A malignant tumor that arises from hepatocytes. "Prickle1 underexpression, with consequent abnormal Wnt signalling, causes hepatocellular carcinoma." (PMID 34964047, 2022). "Expression of the PCP core protein Prickle1 is downregulated in hepatocellular carcinoma whereas both Prickle1 and Vangl1 expression inhibit hepatocellular carcinoma growth in vitro." (PMID 27036398, 2016). "It is also demonstrated in hepatocellular carcinoma that high expression of Prickle1 inhibits active β-catenin though promoting ubiquitination and degradation of Dishevelled." (PMID 27036398, 2016). "In hepatocellular carcinoma cell lines, EZH2, the histone methyltransferase subunit of the polycomb repressor complex, binds to PRICKLE1 promoter and suppresses its expression." (PMID 39314474, 2024). "In hepatocellular carcinoma (HCC), PRICKLE1 negatively regulates Wnt/β-Catenin pathway by binding to DVL3 and facilitating its ubiquitination/degradation." (PMID 26939613, 2016). "In human gastric cancer, EZH2 promotes the activation of Wnt/β-catenin signaling by down-regulating CXXC4 expression, and several other Wnt pathway antagonists, including NKD1, PRICKLE1, PPP2R2B, AXIN2 and SFRP5, were concordantly silenced by EZH2 in hepatocellular carcinomas." (PMID 27926488, 2017).
epilepsy (5 papers, 2013 to 2025). "The observations that SYN1 and PRICKLE1 mutations are associated with epilepsy in humans and mice suggest they are both associated with the pathogenesis of the disease." (PMID 24312498, 2013). "Finally, we determine that two human patient-derived variants of Prickle1 associated with epilepsy result in reduced recruitment of Pk2-LCR to stressed actin." (PMID 40501967, 2025). "Although PRICKLE1 mutations have been linked to epilepsy, the mechanism by which mutations in this gene might contribute to ASD is unknown." (PMID 24312498, 2013). "Before being linked to ASDs, PRICKLE1 was implicated in epilepsy." (PMID 24312498, 2013). "Like PRICKLE1, SYN1 and CNTNAP2 were also initially identified as epilepsy genes, but later studies associated them with ASDs." (PMID 24312498, 2013). "Endogenous Prickle1 and Syn1 co-localize in neurons and physically interact via the SYN1 region mutated in ASD and epilepsy." (PMID 24312498, 2013). "A subset of these genes has been implicated in other neurobehavioral disorders including depression (SLIT3), epilepsy (CLCN2, PRICKLE1), intellectual disability (AP4M1), schizophrenia (WDR60), and Tourette syndrome (OFCC1)." (PMID 24410847, 2014).
progressive myoclonus epilepsy (4 papers, 2014 to 2022). "In humans, individuals with homozygous mutations in the gene PRICKLE1 typically present with progressive myoclonus epilepsy (PME) and motor impairment with ataxia." (PMID 36614124, 2022). "Moreover, mutations in human PRICKLE1 have been associated to seizures, progressive myoclonus epilepsy and autism." (PMID 28697798, 2017). "Also, a mutation in PRICKLE1, which encodes a regulator of the Dishevelled proteins that are intracellular transducers of Wnt signals, has been reported to cause progressive myoclonic epilepsy." (PMID 24463883, 2014).
autism (2 papers, 2016 to 2017). Persistent deficits in social interaction and communication and interaction as well as a markedly restricted repertoire of activity and interest as well as repetitive patterns of behavior. "More recently, variants of PRICKLE1 have been found in individuals with autism." (PMID 27909399, 2016). "Intriguingly, the Prickle1+/- mice exhibit autism-like behaviors, which may result from disrupted interaction with synapsin, a regulator of neurotransmitter release, suggesting that PRICKLE1 plays a critical role in synaptic vesicle regulation." (PMID 27909399, 2016).
cleft palate (2 papers, 2014 to 2021). Cleft palate is a fissure type embryopathy that affects the soft and hard palate to varying degrees. "In conclusion, we have shown that PRICKLE1 variants are associated with cleft palate in humans and a dysfunctional Prickle1 in mice causes a completely cleaved palate." (PMID 24689077, 2014). "PRICKLE1 serves as a signaling factor in the non-canonical Wnt pathway, the disruption of which is known to cause cleft palate and to stunt limb growth." (PMID 34434215, 2021).
colorectal cancer (2 papers, 2022 to 2024). A primary or metastatic malignant neoplasm that affects the colon or rectum. "Also, PRICKLE1 can negatively regulate Wnt/β-catenin activity, which in turn affects the proliferative activity of colorectal cancer cells." (PMID 36861110, 2022). "In addition, in colorectal cancer patients, PRICKLE1 can directly interact with DVL to mediate ubiquitin-proteasome pathway degradation." (PMID 36861110, 2022). "It has been suggested that PRICKLE1 is a disheveled (DVL)-associated protein and exerts tumor suppressive effects by antagonizing DVL recruitment; PRICKLE1 expression is reduced in colorectal cancer tissues compared with normal tissues, and PRICKLE1 deficiency may allow further tumor progression." (PMID 36861110, 2022).
gastric cancer (2 papers, 2017 to 2021). A primary or metastatic malignant neoplasm involving the stomach. "GPC3, GPX3 and PRICKLE1 were the candidate sites selected in the risk prediction model for OS, which indicated that the genes might have potential roles on the malignant behaviors of gastric cancer." (PMID 34926458, 2021). "PRICKLE1 expression is an independent prognostic factor in patients with gastric cancer." (PMID 34926458, 2021).
neuroblastoma (2 papers, 2016 to 2019). Neuroblastoma (NB) is the most common solid, extracranial childhood tumor. "This was also evident from analysis of expression arrays of primary neuroblastoma where high expression of Prickle1 and Vangl2 mRNA are significantly coupled to low-risk disease and good patient survival." (PMID 27036398, 2016). "Here we show that high expression of the PCP core genes Prickle1 and Vangl2 is associated with low-risk neuroblastoma, suppression of neuroblastoma cell growth and decreased Wnt/β-catenin signaling." (PMID 27036398, 2016). "High expression of Prickle1 and Vangl2 corresponded to better survival and low-risk disease across different neuroblastoma expression array datasets." (PMID 27036398, 2016). "We analyzed neuroblastoma expression cohorts and show that high expression of the PCP proteins Prickle1 and Vangl2 correlates with low-risk disease and patient survival." (PMID 27036398, 2016). "Inhibition of Rho-associated kinases (ROCKs) that are important in mediating non-canonical Wnt signaling resulted in increased expression of Prickle1 and inhibition of β-catenin activity in neuroblastoma cells." (PMID 27036398, 2016). "Genetic knock-down of the core PCP genes Prickle1 or Vangl2 resulted in increased growth of neuroblastoma cells and increased active β-catenin levels, while overexpression had the opposite effect." (PMID 27036398, 2016). "Next, we investigated the level of the PCP core proteins Prickle1 and Vangl2 in neuroblastoma cells." (PMID 27036398, 2016). "HA1077 was more effective in stimulating Prickle1 expression, inhibiting β-catenin activity and suppressing neuroblastoma growth as compared to Y-27632." (PMID 27036398, 2016). "High expression of the PCP core proteins Prickle1 and Vangl2 reduce the growth of neuroblastoma cells and correspond to low-stage disease and patient survival." (PMID 27036398, 2016). "Overexpression of Prickle1 or Vangl2 was coupled to decreased neuroblastoma growth and reduced expression of active β-catenin." (PMID 27036398, 2016). "Our experimental data demonstrate that high expression of Prickle1 and Vangl2 reduce the growth of neuroblastoma cells and indicate different roles of PCP proteins in tumorigenic cells compared to normal cells." (PMID 27036398, 2016). "Real-time quantitative PCR demonstrated that Prickle1 expression was inversely correlated to active β-catenin/Axin2 levels in neuroblastoma cells." (PMID 27036398, 2016). "High expression level of PRICKLE1 and VANGL2 correlates with low risk of neuroblastoma." (PMID 31569501, 2019). "Protein expression of Prickle1 and Vangl2 were detected in all tested neuroblastoma cell lines." (PMID 27036398, 2016). "The observation in our study, that high expression of the PCP proteins Prickle1 or Vangl2 reduces the growth of neuroblastoma cells, further supports the notion that key proteins within the PCP signaling pathway may act as tumor suppressors." (PMID 27036398, 2016). "Knockdown of Prickle1 or Vangl2 induced a significant increase in TOPFlash luciferase reporter activity i.e. β-catenin transcriptional activity, compared to siRNA control transfected neuroblastoma cells." (PMID 27036398, 2016). "Overexpression of Prickle1 or Vangl2 significantly inhibited neuroblastoma cell growth compared to cDNA control transfected cells in SK-N-AS (Prickle1 26 % and Vangl2 44 %), SH-EP1 (Prickle1 38 % and Vangl2 60 %), SK-N-BE (Prickle1 53 % and Vangl2 58 %) and SK-N-DZ (Prickle1 83 % and Vangl2 94 %)." (PMID 27036398, 2016). "Further studies showed that the core WNT/PCP signaling components PRICKLE1 and VANGL2 directly inhibit canonical WNT signaling in neuroblastoma cells." (PMID 31569501, 2019). "Transfections with cDNA plasmids or siRNA were used to increase and suppress Prickle1 and Vangl2 expression in neuroblastoma cells and in non-tumorigenic cells." (PMID 27036398, 2016).
Robinow syndrome (2 papers, 2014 to 2019). Robinow syndrome (RS) is a rare genetic syndrome characterized by limb shortening and abnormalities of the head, face and external genitalia. "Curiously, Prickle1 mutants recapitulate the characteristic features of human Robinow syndrome and phenocopy mouse mutants with Wnt5a or Ror2 gene defects, prompting us to explore an association of Prickle1 with the Wnt pathway." (PMID 25190059, 2014). "Our studies implicate Prickle1 as a key component of the Wnt-signaling pathway and suggest that Prickle1 mediates some of the WNT5A-associated genetic defects in Robinow syndrome." (PMID 25190059, 2014). "The phenotypic similarity and its role in mediating Wnt5a/Ror2 signaling make Prickle1 a likely candidate gene for Robinow syndrome." (PMID 25190059, 2014). "Previous studies suggested that the tissue outgrowth and craniofacial defects in Prickle1 mutants were reminiscent of human Robinow syndrome (RS)." (PMID 25190059, 2014). "Furthermore, Prickle1 has been shown to act downstream of Wnt5a and interact with Dvl2, and Prickle1 mutants display characteristics that resemble Robinow syndrome." (PMID 30760477, 2019).
acute lymphoblastic leukemia (1 paper, 2021). Leukemia with an acute onset, characterized by the presence of lymphoblasts in the bone marrow and the peripheral blood. "Compared with the control cell line GM12878, the expression of PRICKLE1 was significantly upregulated in 7 AML cell lines (P < 0.05), but not in human T cell acute lymphoblastic leukemia cell line, Jurkat cells (P > 0.05)." (PMID 34001134, 2021).
brain malformations (1 paper, 2019). "De novo heterozygous PRICKLE1 variants have been linked to congenital brain malformations or myoclonic epilepsies, while two of three APEs with PRICKLE1 p.Ala541Ser variants in our study had non-lesional focal epilepsy and the other had acquired postencephalitic epilepsy." (PMID 31875159, 2019).
central nervous system leukemia (1 paper, 2021). Leukemia infiltrating the central nervous system structures. "We noticed that PRICKLE1 mRNA and protein levels were much higher in AML patients with extramedullary metastasis, especially in patients with central nervous system leukemia (CNSL)." (PMID 34001134, 2021).
Chronic lymphocytic leukemia (1 paper, 2016). "Chronic lymphocytic leukemia (CCL) cells are induced to migrate by Wnt5a in a chemokine gradient manner, which is important in regulating chemotaxis and trans-endothelial migration of CLL cells, apparently through upregulating PCP components including Vangl2, Prickle1, CK1ε, Dvl, and Celsr1." (PMID 27571105, 2016).
diabetes (1 paper, 2017). "Expression levels of ROR2, FZD7, VANGL2 and PRICKLE1 correlated with each other, and these correlations were statistically significant in subjects with and without diabetes, although in most cases they were much stronger in the group with diabetes." (PMID 29229927, 2017). "In addition, WNT5A expression levels in VAT correlated with those of some of the PCP signaling components, such as VANGL2, PRICKLE1, DSH1,2,3 and DIVERSIN/ANKRD6 only in subjects with diabetes." (PMID 29229927, 2017). "Specifically, VAT expression of ROR2, FZD7, VANGL2 and PRICKLE1 correlated with that of DSH1,2,3 and DIVERSIN/ANKRD6 in the diabetes group, but not in most cases in the group without diabetes." (PMID 29229927, 2017).